CD4 (CD4 molecule)
Diseases named in the same sentence as CD4 in open-access papers (continued):
Sharing a sentence is not in itself a finding about the gene and the disease.
cancer (continued). "CD4+ T cells may drive cancer into senescence and are capable of mobilizing both the innate and adaptive immune systems." (PMID 35874660, 2022). "Investigation of tertiary lymphoid structures in human cancer may be a feasible approach to analyze the immune responses of CD4-positive T cells." (PMID 36361781, 2022). "By combining CIBERSORT, EPIC, and quanTIseq algorithms, we identified significantly different TME signatures between the two EAC subtypes and found that EAC subtype 2 had higher levels of CD4+ and CD8+ T cell infiltration as well as M2 macrophages and cancer-associated fibroblasts." (PMID 35631431, 2022). "The cancer tissue SN appeared to induce a partial reversal of the CD4+ activation profile in vitro, resulting in a profile which was very similar to that described for immunotolerant lymphocytes and suggesting that one or more soluble factors from cancer tissue had induced immunotolerance." (PMID 35158758, 2022). "Combined with previous results showing that immune cell infiltration in LUAD is significantly lower than that in normal samples, our results indicated that the SNV of RTK/RAS pathway genes in LUAD would lead to CD4 T cell exhaustion and further result in cancer immune evasion." (PMID 35936718, 2022). "Activated T cells CD4 memory, Tregs, and neutrophils were mainly present in cancer." (PMID 35646079, 2022). "THBS2 expression was significantly correlated with the infiltration levels of B cells in 10 cancer types, dendritic cells in 6 cancer types, macrophages in 12 cancer types, neutrophils in 4 cancer types, CD4 + T cells in 17 cancer types, and CD8 + T cells in 8 cancer types." (PMID 35701829, 2022). "Additionally, activated mast cells, activated/resting dendritic cells, activated NK cells, and naïve B cells were increased, while M2 macrophages and resting CD4 memory cells were decreased in cancer tissues." (PMID 35909892, 2022). "However, in contrast, SCFAs have also shown to be correlated with the expansion of immunosuppressive pro-cancer regulatory CD4+T cells (Treg) and a resistance to anti-cancer immune-checkpoint inhibitor therapy." (PMID 35741028, 2022). "CD4+CD25-FoxP3+ cells were first reported in 2006 in patients with cancer and autoimmune disease." (PMID 36581679, 2022). "The heatmap of the immune infiltration landscape revealed that cluster 1 had a positive correlation with B cells, CD4+ T cells, macrophages cells, mast cells activated and cancer-associated fibroblasts, while it had a negative correlation with monocytes." (PMID 36186456, 2022). "Among the T cells category, the infiltration level of CD4+ memory activated cells was positively correlated with TR-DDR score in 11 cancers significantly (r = 0.17 – 0.47), and the infiltration level of CD4+ memory resting cells was negatively correlated across six cancer types (r = -0.13 – -0.55)." (PMID 36081518, 2022). "In this study, high TIGIT expression promoted the infiltration levels of CD8 T cells, M1 macrophages, naive B cells, activated memory CD4 T cells, Tregs and activated NK cells while inhibiting the infiltration levels of activated dendritic cells and mast cells in most of the cancers included." (PMID 36211383, 2022). "Moreover, the ratios of immune-stimulatory/immune-inhibitory signatures (CD8+/CD4+ regulatory T cells) also showed significant inverse correlations with DEPTH2 scores in pan-cancer (ρ = − 0.32, P = 2.05 × 10–256) and in 18 cancer types (P < 0.05)." (PMID 35365157, 2022). "Several studies correlate Eomes expression with improved protection against cancers by CD4 T cells." (PMID 36358898, 2022). "Overall, therapeutic vaccination incorporating CD4+ T cell target could be an efficient approach in various cancers, especially when combined with ICI therapy." (PMID 35008422, 2022). "CD4+ T cells play a central role in adaptive immune responses against infections and cancer through the recognition of peptides coming from pathogens or specifically found in cancer cells." (PMID 35494241, 2022).
cancer (continued). "Our results indicate that of all the cells in cancer tissues, CD4+ T cells may predict pathological response to platinum-containing NAC in patients with HRD-high TNBC." (PMID 35462552, 2022). "Additionally, KIF21B was positively correlated with CD4+ T cell and neutrophil cell, which involved in regulation of immune infiltrate of cancer cells." (PMID 36451772, 2022). "The activated memory CD4 T cells, activated dendritic cells, resting dendritic cells, M1 macrophages, and neutrophils were positively associated with ARPC2 in most tumors, whereas naïve CD4 T cells did not correlate with ARPC2 expression in 33 cancer types." (PMID 35733852, 2022). "Early findings suggested that abundant CD8+ T cells and CD4+ T cells could be prognostic indicators for the clinical outcome in cancers." (PMID 35840882, 2022). "Furthermore, we found a significant positive association between EFNB1 and different immune response cells toward cancer, such as B cells, CD4+ T cells, CD8+ T cells, neutrophils, macrophages, and DCs." (PMID 36052169, 2022). "We anticipate that this resource and the associated computational tools to predict phosphorylated HLA-II ligands in different contexts will facilitate the discovery of potential new targets for CD4+ T cell recognition in infectious diseases and cancer immunotherapy." (PMID 35494241, 2022). "Another phase 2 trial in advanced urothelial carcinoma certified that cabozantinib, a multikinase inhibitor, could also be a new therapeutic option for these cancer patients by lowering the percentage of Tregs among CD4+ T cells and the G-MDSC populations." (PMID 35053426, 2022). "T helper 1 (Th1) polarized CD4+ T cells sustain inflammation and cytotoxic cell function and survival through production of IFN-γ and other cytokines (IL-15, IL-12) and are usually associated with a good prognosis in several cancer types." (PMID 35874810, 2022). "Therefore, in this study, we determined the cytokine profile of CD4+ and CD8+ T cells as well as the frequency of Foxp3+ Treg cells in the TDLNs of HNSCC and assessed their association with cancer parameters." (PMID 36376825, 2022). "In addition, TEM induced systemic anti-cancer immunity by increasing the number and activation of CD4+ and CD8+ T cells." (PMID 36077620, 2022). "For instance, it has been reported that CD4+ TILs may change from effectors to suppressors when cancer progresses." (PMID 36428728, 2022). "Increased Bregs could convert CD4+CD25- T cells into CD4+Foxp3+ Tregs in cytological experiments and are associated with cancer progression and worse survival." (PMID 36168626, 2022). "The results illustrated that the expression level of NT5E is positively correlated several immune cells infiltration in almost all cancers, such as memory CD4+ T-Cells and M1-polarized macrophages, while negatively related to plasma cells and T follicular helper cells in pan-cancer." (PMID 36569293, 2022). "At cancer diagnosis, the median CD4 cell count was 408 cells/ μL (IQR 327–571)." (PMID 36185101, 2022). "Other cell types (such as CD4+ T cells) may also contribute to immune surveillance, thereby enhancing the anti-cancer immune response ability." (PMID 35875124, 2022). "As a result, the body’s capacity to inhibit cancer cells may be impacted when inflammation results in prolonged lymphocytopenia, including CD4+ and CD8+ T lymphocytes." (PMID 36212433, 2022). "Moreover, M2 macrophages, T follicular helper cells (Tfh cells), and resting CD4 memory T cells were the three immune cell types most strongly correlated with THBS2 expression across 21 cancer types." (PMID 35701829, 2022). "Moreover, the levels of resting mast cells, naive B cells, and resting memory CD4+ T cells were negatively correlated in more than 10 types of cancers." (PMID 36202136, 2022). "Likewise, radiation-induced damage was also observed in cancer patients with a decreased CD4+/CD8+ ratio, suggesting that the immune system was greatly reduced." (PMID 36555814, 2022).
cancer (continued). "Immune infiltration analysis revealed a significant correlation between the expression of EZH2 and the abundance of immune cell infiltration, including B cells, CD4+ T cells, CD8+ T cells, macrophages, neutrophils, dendritic cells, and cancer-associated fibroblasts (CAFs), in LIHC tissues." (PMID 35627262, 2022). "The blockade of TGFβ signaling in CD4+ T cells could restore the responses of helper T cells and inhibit cancer progression, which is mainly mediated by the induction of vascular system reorganization." (PMID 35707265, 2022). "CD4 memory-activated T cells, resting NK cells, M0 macrophages, M1 macrophages, activated mast cells, and neutrophils had an increased infiltration rate in cancer tissues." (PMID 35057760, 2022). "These CD4+ T-cell subsets can play opposing roles in cancer progression." (PMID 36010994, 2022). "UV1 is a therapeutic cancer vaccine that consisted of three synthetic long peptides of the enzyme telomerase (hTERT) which could induce CD4+ T helper type 1 (Th1) cells." (PMID 35342400, 2022). "In cancer tissues, the CD4+T cell cluster (C66) had the highest percentage, reaching 8.74%." (PMID 35725444, 2022). "Thus, CD4+ T cell activation in established cancers can transform “cold” tumors into “hot” immunogenic tumors that are responsive to conventional immunotherapeutics." (PMID 35657353, 2022). "Bacterial induction of cancer death is generally attributed to bacteria stimulating the body’s immune system, which destroys invading bacteria while killing malignant cells via released cytokines from activated CD4+ helper and CD8+ cytotoxic T cells." (PMID 36119107, 2022). "Furthermore, NAFLD for lymphocyte and CD3+ counts, CVD for CD3+CD4+ and CD3+CD8+ percentage, DM for CD3+CD8+ percentage, and cancer for CD3+ percentage were all shown to be risk factors." (PMID 35865540, 2022). "However, Foxp3+CD4+ Tregs have been the divas of cancer immunobiology in receiving the lion’s share of attention." (PMID 35703176, 2022). "There were more immune cells infiltrated in patients with high riskScore, such as Tregs, cancer-associated fibroblasts (CAF), T follicular helper cell, memory-activated CD4+ T cell, and macrophage M0 cells, which was consistent with pyroptosis subtypes and pyroptosis-score." (PMID 35846134, 2022). "CD4+ and CD8+ lymphocytes are implied in the prevention of neoplastic proliferation and invasion, CD8+ T cell counts are consistently associated with better survival in many types of cancer." (PMID 35158991, 2022). "However, the potential efficacy of activating CD4+ T cells against late-stage cancers remains largely unexplored." (PMID 36467403, 2022). "Therefore, we developed a reliable pipeline to effectively predict CD4+ T-cell immune responses against cancer and infectious diseases." (PMID 35785204, 2022). "Although CD8+ CTLs are best known as responders to eradicate malignant cells, studies have shown that CD4+ cytotoxic T cells existing naturally in the context of infectious diseases and cancers could directly kill infected or cancer cells." (PMID 35928827, 2022). "Professional APCs possess all the machinery to optimally process and present antigens to T cells, while malignant tumor cells lack some of the processing machinery needed to generate the large repertoire of functional HLA peptide complexes necessary for a robust CD4+ T cell response." (PMID 35162988, 2022). "In OV, CD161 was highly expressed in CD4 T cells, cancer cells, and fibroblasts." (PMID 36660546, 2022). "The coculture of CD4 Th cell lines from C5 with SW480 cell line showed a lower level of IL-17A because the SW480 cancer cells underwent apoptosis while high IL-6 was detected due to the high proliferation of CD4 Th cell lines from C5 which cause the cell cytotoxicity." (PMID 37529004, 2022). "CD4+ and CD8+ T cells can specifically recognize tumor-associated antigens from cancer cells." (PMID 36142615, 2022).
cancer (continued). "Interestingly, CD4 + T cells move from sender in normal tonsil into receiver in HNSCC-TIL that argues for an alteration in cancer-related immune response in this context." (PMID 36157879, 2022). "CD4 T cells play an important role in cancer immunology and immunotherapy." (PMID 36299580, 2022). "Moreover, the expression of USP10 correlated strongly with the infiltration level of dendritic cells in 10 cancers, with neutrophils in 24 cancers, with macrophages in 18 cancers, with CD4+ T cells in 13 cancers, and with CD8+ T cells in 15 cancers." (PMID 35433424, 2022). "As an immunosuppressive CD4+ subset, Treg cells play a crucial role in cancer immune evasion." (PMID 35285006, 2022). "Additionally, a lot of attention has been devoted to the role and function of CD4+ regulatory T cells (Tregs) in cancer." (PMID 36159781, 2022). "Cancer patients also have a CD4 repertoire for Vim116-135Hcit." (PMID 35464453, 2022). "Its expression was positively related to infiltration levels of T cell CD4+ memory resting, T cell CD4+ memory, T cell CD4+, Tregs and mast cell in over 8 types of cancers, while it was negatively correlated with T cell CD4+ Th1, Macrophage and T cell NK in more than 8 types." (PMID 36212008, 2022). "However, the potential efficacy of inducing CD4+ T cell response to prevent and treat cancer remains mostly unexplored." (PMID 36467403, 2022). "Different immune cells subpopulations are involved in the response triggered by these therapeutic agents, mainly represented by T reg, CD8 and CD4 T cells, but recent studies have shown that also NK cells actively participate in the successful outcome of anti-cancer treatment." (PMID 36358708, 2022). "Infiltration of resting memory CD4+ T cells and M1 macrophages positively associated with STAT2 expression; however, STAT2 negatively correlated with the infiltration of activated mast and memory B cells in most cancer types." (PMID 36176415, 2022). "Intermediate CD4+:CD8+ ratios maximize cancer killing and increase CAR T-cell proliferation." (PMID 35903149, 2022). "Both hepatitis B virus and Helicobacter pylori can induce the enrichment of MDSCs in cancer tissues, resulting in an imbalance in the proportion of CD4+ and CD8+ T-cell subsets and producing the inactivation of antitumour immunity and the malignant proliferation of cancer cells." (PMID 35435776, 2022). "Activated CD4+ memory T cells are also related to better survival in different cancer types." (PMID 36189269, 2022). "In addition, studies have demonstrated the modulation effects of mTORC1/2 on various human cells such as CD4, CD8, Treg, TAMs, cancer-associated fibroblasts (CAF), endothelial cells, and myeloid-derived suppressor cells (MDSCs)." (PMID 36428613, 2022). "CD4+ Th1 cells exert powerful antitumor immune effects against numerous types of cancers." (PMID 35874660, 2022). "According to ESTIMATE scores, there were favorable associations between NNMT expression and stromal and immune cell composition in the TME of 31 malignancies, and therefore a strong relationship with naïve B cells, M1 macrophages, naïve CD4 T cells, and resting NK cells." (PMID 36386816, 2022). "In the current study, in the non-carcinoma biliary tract tissues, only naïve CD4+ and naïve CD8+ T cells were detected, whereas in cancer tissues, 4 distinct T cell subclusters were identified, as the emergence of cytotoxic CD8+ T cells and FOXP3+ Treg cells." (PMID 35219893, 2022). "According to the current literature, immune cells that are crucial in the fight against cancers include T-helper-1 (Th1) cells, which are CD4+ T-cells that produce IFN-γ, CD8+ cytotoxic T-lymphocytes (CTL), mature dendritic cells (DC), NK cells, and macrophages." (PMID 34371830, 2021).
cancer (continued). "For one, it is necessary to note that the patients using PIs in our report were at greater baseline hematologic risk, as evidenced by the significantly greater proportion of patients with a CD4 count equal to or less than 200 at time of cancer diagnosis (28.1% vs 12.1%, p < 0.01)." (PMID 34225709, 2021). "For proper cancer defense, both CD4+ T cells and CD8+ T cells are required." (PMID 34439305, 2021). "Antigens used in vaccination may span from use of peptide fragments or full proteins, DNA and mRNA, or even bulk cancer cell lysates to stimulate CD4+ TH1 responses in vivo." (PMID 34012451, 2021). "Parallel to this revival of interest in CD4+ T cells, there has also been significant research directed at producing a universal cancer vaccine based on promiscuous class II epitopes from self-molecules such as survivin (an inhibitor of apoptosis) and telomerase reverse transcriptase (TERT)." (PMID 32457487, 2021). "The inflammatory T cell phenotype seen in Selplg−/− mice provides support for the therapeutic targeting of PSGL-1 on CD4+ T cells in cancer, as it may provide a way to lessen immune suppression and increase the activation of T cells." (PMID 33708224, 2021). "In the group with high TMB level, higher infiltration of CD8+ T cells, CD4+ T cells, and other immune cells could be observed in the cancer tissue." (PMID 34367284, 2021). "Also, fibroblasts differentiated from bone marrow CD4+ monocytes enhance the cancer hepatocyte-like properties of LC cells through the secretion of SPP1 and activation of the PIK3K/AKT pathway." (PMID 34671675, 2021). "The study of CD4+ T cells has tremendous potential to contribute to cancer immunotherapy." (PMID 34966745, 2021). "Overall, while there are clearly conserved features of cytotoxic CD4+ T cells across both cancer and other immune contexts, and some possible divergent features, this requires further study to better elucidate the specific program and activation requirements in the context of human cancer." (PMID 34910940, 2021). "Collectively, our findings highlight the molecular and physiological events that occur during CD4+ T cell exhaustion, meaning they may serve as the basis for the improvement of cancer immunotherapy based on adoptive CAR-T transfer." (PMID 34439305, 2021). "Here, we sought to take advantage of both cancer vaccine and immune-modulator properties to impact not only the quantity but also the quality of both CD8 and CD4 T cells, establishing a combination immunotherapy able to effectively tackle different types of cancers." (PMID 34276686, 2021). "Altogether, it seems that the frequency of CD8+ T cells, CD4+ T cells, and Tregs may be affected by the presence of cancer cells." (PMID 32808188, 2021). "This suggests that the generation of cytotoxic CD4+ T cells may be a complex and ongoing dynamic process with distinct microenvironmental cues in cancer patients." (PMID 34910940, 2021). "NK cells, CD8+ CTL and CD4+ Th1 cells are the important weapons to fight against cancer cells." (PMID 35127500, 2021). "Indeed it has been suggested that cell-mediated immune responses by T cells bearing CD4 that recognize antigen presented by class II MHC play a crucial role in cancer development by PV infections." (PMID 34179154, 2021). "HSF2 expression was significantly linked with the abundance of infiltrating CD4+ T cells in 12 types of cancer, CD8+ T cells in 16 types of cancer, B cells in 16 types of cancer, macrophages in 17 types of cancer, neutrophils in 18 types of cancer, and DCs in 18 types of cancer." (PMID 35087869, 2021). "Interestingly, mainly the CD8 T lymphocytes showed a distribution in between the cancer cells in the so-called hot tumors, while CD11b-positive myeloid cells and CD4 T lymphocytes were less frequently found in between cancer cells." (PMID 34778030, 2021). "In CD4+ T cell exhaustion induced by cancer cells, global transcriptomic changes occurred." (PMID 34439305, 2021).